CREB1 (cAMP responsive element binding protein 1)
Description:
Phosphorylation-dependent transcription factor that stimulates transcription upon binding to the DNA cAMP response element (CRE), a sequence present in many viral and cellular promoters (By similarity). Transcription activation is enhanced by the TORC coactivators which act independently of Ser-119 phosphorylation. Involved in different cellular processes including the synchronization of circadian rhythmicity and the differentiation of adipose cells (By similarity). Regulates the expression of apoptotic and inflammatory response factors in cardiomyocytes in response to ERFE-mediated activation of AKT signaling (By similarity).
Synonyms: CREB-1; CREB
Tractability: PROTAC: UniProt records ubiquitination sites on it; ubiquitination databases record sites on it; its protein half-life has been measured; a small molecule that binds it is known.
Target class: Transcription factor
Gene: Protein-coding gene on chromosome 2 (207,529,737 to 207,605,988, forward strand). Ensembl gene ENSG00000118260.
Subcellular location: Nucleus
Subcellular location (Human Protein Atlas): Nucleoplasm; Basal body; Centrosome; Cytosol
Pathways (Reactome):
Signal Transduction: AKT phosphorylates targets in the nucleus; CREB phosphorylation; CaMK IV-mediated phosphorylation of CREB; Estrogen-dependent nuclear events downstream of ESR-membrane signaling; Gastrin-CREB signalling pathway via PKC and MAPK; NGF-stimulated transcription; NOTCH2 intracellular domain regulates transcription; PKA-mediated phosphorylation of CREB
Developmental Biology: NCAM signaling for neurite out-growth; Regulation of MITF-M-dependent genes involved in pigmentation; Transcriptional and post-translational regulation of MITF-M expression and activity; Transcriptional regulation of granulopoiesis
Disease: ADORA2B mediated anti-inflammatory cytokines production; Constitutive Signaling by AKT1 E17K in Cancer; FCGR3A-mediated IL10 synthesis; HCMV Early Events
Neuronal System: CREB1 phosphorylation through NMDA receptor-mediated activation of RAS signaling; CREB1 phosphorylation through the activation of Adenylate Cyclase; CREB1 phosphorylation through the activation of CaMKII/CaMKK/CaMKIV cascasde
Circadian clock: Expression of BMAL (ARNTL), CLOCK, and NPAS2; Phosphorylated BMAL1:CLOCK (ARNTL:CLOCK) activates expression of core clock genes
Cellular responses to stimuli: Heme signaling
Organelle biogenesis and maintenance: Transcriptional activation of mitochondrial biogenesis
Gene Ontology:
Molecular function: cAMP response element binding; DNA-binding transcription activator activity, RNA polymerase II-specific; DNA-binding transcription factor activity; DNA-binding transcription factor activity, RNA polymerase II-specific; enzyme binding; identical protein binding; protein binding; RNA polymerase II cis-regulatory region sequence-specific DNA binding; RNA polymerase II-specific DNA-binding transcription factor binding; sequence-specific double-stranded DNA binding; arrestin family protein binding; DNA binding; histone acetyltransferase binding; Hsp70 protein binding; RNA polymerase II transcription regulatory region sequence-specific DNA binding; sequence-specific DNA binding; transcription cis-regulatory region binding; transcription coactivator binding
Biological process: cAMP/PKA signal transduction; cellular response to forskolin; mRNA transcription by RNA polymerase II; negative regulation of transcription by RNA polymerase II; positive regulation of transcription by RNA polymerase II; protein phosphorylation; response to purine-containing compound; cellular response to retinoic acid; circadian rhythm; negative regulation of apoptotic process; positive regulation of DNA-templated transcription; positive regulation of fat cell differentiation; positive regulation of lipid biosynthetic process; protein stabilization; regulation of transcription by RNA polymerase II; response to glucagon; signal transduction; cell differentiation; cellular response to fatty acid; cellular response to growth factor stimulus; cellular response to insulin-like growth factor stimulus; cellular response to nerve growth factor stimulus; cellular response to platelet-derived growth factor stimulus; cellular response to transforming growth factor beta stimulus; chemotaxis to arachidonate; and 26 more
Cellular component: ATF4-CREB1 transcription factor complex; euchromatin; nucleoplasm; nucleus; RNA polymerase II transcription regulator complex; chromatin; axon; mitochondrial matrix; transcription regulator complex
Genetic constraint (gnomAD): Loss-of-function variants: 2 observed, 33.26 expected, observed/expected ratio (o/e) 0.0601, 90% interval 0.024 to 0.19. The upper end of that interval is the gene's LOEUF score, 0.19, which puts it in group 1 of 6, group 1 being the genes least tolerant of losing a copy. Missense variants: 163 observed, 346.21 expected, observed/expected ratio (o/e) 0.47, 90% interval 0.41 to 0.54. Synonymous variants: 106 observed, 125.6 expected, observed/expected ratio (o/e) 0.84, 90% interval 0.72 to 0.99.
Homologues: Orthologues: chimpanzee CREB1 (100% identical), dog CREB1 (100% identical), macaque CREB1 (100% identical), rabbit CREB1 (100% identical), mouse Creb1 (99% identical), guinea pig CREB1 (99% identical), rat Creb1 (99% identical), tropical clawed frog creb1 (97% identical), zebrafish creb1b (90% identical), pig CREB1 (85% identical), Drosophila melanogaster CrebB (32% identical), Caenorhabditis elegans crh-1 (32% identical), and 2 more. Paralogues in human: CREM (57% identical), ATF1 (51% identical), CREB3L1 (18% identical), CREB3L3 (17% identical), CREB3L4 (17% identical), CREB3L2 (16% identical), ATF6 (16% identical), ATF6B (15% identical), CREB3 (13% identical).
Diseases named in the same sentence as CREB1 in open-access papers:
CREB1 is named in the same sentence as 521 diseases in open-access papers, as found by Europe PMC text mining. Sharing a sentence is not in itself a finding about the gene and the disease. The quoted sentences say what the papers report.
depression (340 papers, 2006 to 2026). "On a genetic level, CREB1 polymorphisms have been linked to schizophrenia, bipolar disorder, and major depressive disorder." (PMID 39518903, 2024). "We found that the CREB1 rs2253206 AA and rs10932201 GA genotypes were associated with an increased risk of depression." (PMID 36597080, 2023). "These contradictory results imply that further study of CREB1 is urgently needed to describe the overall picture of the genetic and biological basis of CREB1 and its protein product in susceptibility to depression." (PMID 36597080, 2023). "This study provides preliminary evidence for the correlation between rs2253206 and rs10932201 polymorphisms of CREB1 and susceptibility to depression." (PMID 36597080, 2023). "CSDS triggered changes in stress-associated transcripts Creb1 and Pdyn in the nucleus accumbens, a brain area implicated in the etiology of depressive disorders." (PMID 36192377, 2022). "Previous familial studies of recurrent, early onset major depressive disorder showed that genes at chromosome 19p13 interact with CREB1 to increase the risk of depression." (PMID 32555505, 2020). "In particular, changes in brain expression of Creb1 and Bdnf are closely linked to depression pathology and antidepressant efficacy." (PMID 31442236, 2019). "The CREB1 has been implicated in the pathophysiology of depression and in the response to antidepressant treatment." (PMID 28225778, 2017). "The minor allele A for SNP rs6785 has been associated with the risk for depression/bipolar disorder in Caucasians as well as smaller hippocampus volume and increased CREB1 mRNA level in the prefrontal cortex of healthy Caucasian and African Americans." (PMID 28559842, 2017). "This group provided the strongest linkage evidence in our study, where the linkage signal spans the genomic region containing the gene cAMP responsive element binding protein 1 (CREB1) which has been implicated as a candidate gene for depression." (PMID 20300526, 2010). "The top gene networks in both categories displayed similarities, as they included numerous signal transduction and transcription components of the mitogen-activated protein kinase pathway and other genes previously implicated in depression (CREB1, SAT1)." (PMID 20376317, 2010). "In order to verify their correlation with depression and explore their possible mechanisms, we investigated the association of the CREB1 SNPs rs2253206 and rs10932201 and the GRM7 rs162209 with first onset, family history, and suicidal tendency in patients with depression." (PMID 36597080, 2023). "Additionally, a meta-analysis showed that an SNP located in CREB1 was associated with depression, and that a decrease in CREB1 expression may be a risk factor for depression." (PMID 36597080, 2023). "Thus, the present findings indicate that the CREB1 polymorphisms rs2253206 and rs10932201 may be related to the occurrence of depression." (PMID 36597080, 2023). "Level of depression; daily life function; and serum levels of CREB1, BDNF, and 5-HT.Results: significant." (PMID 41562835, 2026). "In contrast, other studies show that miR-124a overexpression promotes depression-like behaviors, whereas its inhibition yields antidepressant-like effects, potentially via CREB1 and BDNF upregulation." (PMID 41179817, 2025). "CREB1, a transcription factor regulating depression-related genes, is influenced by stress and inflammatory responses, with Amuc_1100Δ80 potentially modulating the 5-HTR1A-CREB-BDNF pathway via toll-like receptor 2 (TLR2) interactions." (PMID 40108902, 2025). "Our present findings are consistent with the findings of previous studies, and verifying the correlation between CREB1 and depression in Chinese people." (PMID 36597080, 2023). "In this study, we explored the association between SNPs of candidate genes CREB1 and GRM7 in depression among Chinese people." (PMID 36597080, 2023).
depression (continued). "Depression model rats showed overexpression of miR-124 and down-regulation of CREB1 and BDNF in the hippocampus." (PMID 34054732, 2021). "In this study, interactions among miR‐199a‐5p, the WNT pathway, and the CREB1/BDNF axis in the development of depression were investigated." (PMID 34333859, 2021). "This also the case with the expression of CREB1 and BNDF, both of which were closely associated with depression." (PMID 30298999, 2018). "Knockout mice for two Creb1 isoforms inhibit pup retrieval and nest building behaviors, and has been identified as a possible candidate gene for depression." (PMID 24423034, 2014). "Cyclic adenosine monophosphate response element binding protein (CREB1)—a transcription factor that controls the transcription of numerous neuronal expressed genes—has been shown to be related to both the pathogenesis and treatment of depression." (PMID 36597080, 2023). "The purpose of this study was to investigate whether the CREB1 polymorphisms rs2253206 and rs10932201 and the GRM7 polymorphism rs162209 are associated with the risk of depression." (PMID 36597080, 2023). "However, there are few reports on the genetic susceptibility of CREB1 SNPs rs2253206 and rs10932201 and GRM7 SNPs rs162209 involved in depression." (PMID 36597080, 2023). "While knocking down miR-124 improved depression-like behavior in depression rats, which might be related to the increased expression of CREB1 and BDNF in the hippocampus." (PMID 34054732, 2021). "Another study reported that inhibited function of the CREB1/BDNF/NTRK2 pathway had a negative impact on the risk mechanism of depression." (PMID 34333859, 2021). "Cyclic adenosine monophosphate-responsive element-binding protein 1 (CREB1), as a representative indicator of the hippocampus of depressed rats, was reported to implicate depression via down-regulation, and thus was considered as the potential target of XYD treatment." (PMID 32190105, 2020). "CREB1 regulates gluconeogenesis, lipid metabolism, and insulin signaling pathways, and the activity of its transcriptional promoter is associated with the pathogenesis of TD2, adipogenesis, and major depressive disorder." (PMID 32316129, 2020). "Overexpression of mmu_circ_0001223 in PC12 significantly promoted CREB1 and BNDF proteins levels, which might be an important mechanism underlying the inhibition of depression by SLPN." (PMID 30298999, 2018). "Moreover, oxidative damage could affect various genes such as CREB1 and BDNF, associated with neuronal regeneration, depression, and cognition." (PMID 32841551, 2020). "More importantly, the overexpression of mmu_circ_0001223 in PC12 cells by lentiviral system resulted into remarkable increase of CREB1 and BNDF expression, showing that the implication of mmu_circ_0001223 in depression might be mediated by the modulation of CREB1 and BNDF‐related signaling pathways." (PMID 30298999, 2018). "Of interest, independent CREB1 haplotypes have been associated with selective serotonin receptor inhibitor (SSRI) remission, emergent suicidal ideation during SSRI treatment and treatment resistant depression, features previously linked to latent bipolarity among depressed subjects." (PMID 24885933, 2014). "These few studies, implicating the roles of synaptic plasticity candidate genes BDNF and CREB1, as well as serotonin receptor gene HTR2A and folate pathway gene MTHFD1L, have exclusively focused on depression as a relevant disorder, or on depressive symptoms." (PMID 34577549, 2021). "Taking together, these results showed that mmu_circ_0001223‐regualted CREB1 and BNDF expression was involved in the inhibition of depression by SLPN in CUMS mice." (PMID 30298999, 2018). "Previous reports showed the CREB1 and BNDF‐related signaling pathways were involved in the pathogenesis of depression and also depression treatment." (PMID 30298999, 2018).
depression (continued). "Previous work has shown that the rs2253206 and rs10932201 in CREB1 and rs162209 in GRM7 may light on the pathogenesis of depression." (PMID 36597080, 2023). "Apart from CREB1, metabotropic glutamate receptor 7 (GRM7), which mediates the effect of glutamate on neurotransmitter release and cell excitability, has been found to be related to depression." (PMID 36597080, 2023). "Furthermore, differences between MDD and BPD were seen for matrix-associated growth factors APP and SPARC, immune gene TNF, and transcription factors CREB1, NFKB1, and NR3C1 when controlling for depression severity, age, and medication use." (PMID 24143878, 2013).
Cognitive impairment (222 papers, 2011 to 2026). Abnormal cognition is characterized by deficits in thinking, reasoning, or remembering. "Among the co-regulated TFs, CREB1 has been identified as a risk factor for cognitive impairment in patients with BD." (PMID 39290304, 2024). "Neob prevented ISO anesthesia-induced cognitive impairment by suppressing apoptosis and inflammation through upregulating CREB1." (PMID 37120983, 2023). "Neob treatment attenuated ISO-induced brain inflammation as well as synaptophysin in neonatal mice by upregulating the CREB1 phosphorylation level, thereby alleviating cognitive impairment in neonatal mice." (PMID 37120983, 2023). "In general, CREB1 can alter the expression of genes related to neuronal growth, survival, and plasticity, and has been proposed as a drug target to ameliorate cognitive decline in aging and cognitive disorders." (PMID 39143450, 2025). "In this study, we examined whether three independent CREB1 SNP genotypes contribute to individual differences in the performance level and longitudinal change of memory and executive function in older adults free of cognitive impairment." (PMID 28559842, 2017).
breast cancer (161 papers, 2008 to 2026). A primary or metastatic malignant neoplasm involving the breast. "A study showed that CREB1 levels were significantly elevated in tumour tissues of breast cancer patients and were strongly associated with poor prognosis, breast cancer metastasis and lymph node involvement." (PMID 40928004, 2025). "Our analysis of publicly available gene expression profiles revealed that high levels of CREB1 are associated with better prognosis in ERα-positive breast cancers, i.e., that they must have a protective effect in patients as well, and not just in cells." (PMID 30456355, 2018). "Our data demonstrated that a specific decrease of GABARAPL1 expression in breast cancers was associated with both DNA methylation and histone deacetylation and that CREB-1 recruitment on GABARAPL1 promoter was required for GABARAPL1 expression." (PMID 26474850, 2015). "Recently, overexpression of CREB1 has been reported to be associated with poor prognosis in non-smokers with non-small cell lung cancer and in patients with breast cancer." (PMID 25825983, 2015). "We found that MTORT1 could inhibit the proliferation and migration of breast cancer cells, and could serve as a miRNA sponge to up-regulate the nucleus-encoded genes, CREB1 and STK4, by binding to miR-26a-5p." (PMID 34141617, 2021). "Moreover, high levels of CREB1 are associated with good prognosis in ERα-positive breast cancer patients, which may be because of its ability to promote ERα functions, thereby maintaining it as a successful therapeutic target." (PMID 30456355, 2018). "Besides, high expression of CREB1 is associated with metastasis in gastric and breast cancer, while knockdown of CREB1 could inhibit liver cancer cell migration." (PMID 27801665, 2016). "Previous studies have highlighted CREB1’s involvement in colorectal cancer, breast cancer, and thyroid cancer." (PMID 40722651, 2025). "Recent studies have shown that overexpression of CREB1 can act as a transcription factor to promote the proliferation and migration of breast cancer cells." (PMID 40928004, 2025). "More specifically, overexpression of Creb1 promotes induction of estrogen receptor α target genes in a breast carcinoma cell line." (PMID 38711951, 2024). "In agreement, high phospho-CREB1/ATF1 intensity is associated with poor overall survival and disease-free survival in breast cancer (P = 0.007 and P < 0.001, respectively)." (PMID 37463926, 2023). "Further, the genes were also enriched for targets of several transcription factors, like NELFE, E2F4 and CREB1 which are known to play key roles in several cancers, including breast cancer." (PMID 36584096, 2022). "Whereas CREB1 was found to reduce the apoptosis process and increase cell proliferation in breast cancer, PRKACA plays a key role in tumorigenesis and development of BC." (PMID 33910530, 2021). "LINC01857 is thought to promote breast cancer progression by regulating CREB1 activation via interacting with CREBBP." (PMID 34458145, 2021). "This confirms the oncogenic potential of CREB1 as high protein levels were observed in a number of other solid tumors including breast cancer, non-small-cell lung cancer, diffuse malignant mesothelioma and melanoma." (PMID 32300145, 2020). "Binding of epidermal growth factor (EGF) to epidermal growth factor receptor (EGFR) leaded to the phosphorylation of CREB1 which resulted in a series of genes expression correlated with the progression of breast cancer." (PMID 31754343, 2019). "In MCF-7 and MDA-MB-231 cells, VASP overexpression significantly reversed the inhibitory effect of CREB1 knockdown on the migration of breast cancer cells." (PMID 31754343, 2019). "Aberrant expression of CREB1 has been observed in various kinds of cancers, including breast cancer; and CREB1 is also involved in tumor proliferation, invasion, and metastasis." (PMID 30988073, 2019).